SELENON (selenoprotein N)
Description:
[Isoform 2]: Plays an important role in cell protection against oxidative stress and in the regulation of redox-related calcium homeostasis. Regulates the calcium level of the ER by protecting the calcium pump ATP2A2 against the oxidoreductase ERO1A-mediated oxidative damage. Within the ER, ERO1A activity increases the concentration of H(2)O(2), which attacks the luminal thiols in ATP2A2 and thus leads to cysteinyl sulfenic acid formation (-SOH) and SEPN1 reduces the SOH back to free thiol (-SH), thus restoring ATP2A2 activity. Acts as a modulator of ryanodine receptor (RyR) activity: protects RyR from oxidation due to increased oxidative stress, or directly controls the RyR redox state, regulating the RyR-mediated calcium mobilization required for normal muscle development and differentiation. Essential for muscle regeneration and satellite cell maintenance in skeletal muscle.
Synonyms: SelN; SEPN1; RSS; CFTD; CMYO3; CMYP3; MDRS1; RSMD1
Tractability: Antibody: UniProt predicts a signal peptide or a membrane-spanning region. PROTAC: ubiquitination databases record sites on it.
Gene: Protein-coding gene on chromosome 1 (25,800,193 to 25,818,221, forward strand). Ensembl gene ENSG00000162430.
Subcellular location: Endoplasmic reticulum membrane (Isoform 2)
Subcellular location (Human Protein Atlas): Cytosol
Gene Ontology:
Molecular function: protein binding; calcium ion binding
Biological process: calcium ion homeostasis; positive regulation of response to oxidative stress; regulation of ryanodine-sensitive calcium-release channel activity; skeletal muscle fiber development; skeletal muscle satellite cell maintenance involved in skeletal muscle regeneration
Cellular component: endoplasmic reticulum membrane; endoplasmic reticulum; mitochondria-associated endoplasmic reticulum membrane contact site; mitochondrial membrane; mitochondrion
Genetic constraint (gnomAD): Loss-of-function variants: 44 observed, 56.31 expected, observed/expected ratio (o/e) 0.78, 90% interval 0.61 to 1. The upper end of that interval is the gene's LOEUF score, 1, which puts it in group 4 of 6, group 1 being the genes least tolerant of losing a copy. Missense variants: 623 observed, 686.67 expected, observed/expected ratio (o/e) 0.91, 90% interval 0.85 to 0.97. Synonymous variants: 296 observed, 287.45 expected, observed/expected ratio (o/e) 1.03, 90% interval 0.94 to 1.13.
Gene-disease validity (ClinGen):
ClinGen rates the evidence that SELENON causes each of these diseases.
SELENON-related myopathy (autosomal recessive): Definitive. Myopathy caused by pathogenic variants in SELENON that is congenital or present early in childhood with neonatal hypotonia, delayed motor development, axial muscle weakness, scoliosis, and significant respiratory involvement.
Homologues: Orthologues: chimpanzee SELENON (91% identical), pig SELENON (87% identical), mouse Selenon (84% identical), rat Selenon (84% identical), guinea pig SELENON (83% identical), dog SELENON (61% identical). Paralogues in human: HOATZ (6% identical), BEND2 (3% identical).